NKILA (NF-kappaB interacting lncRNA)
Diseases named in the same sentence as NKILA in open-access papers (continued):
Sharing a sentence is not in itself a finding about the gene and the disease.
lymph node metastasis (5 papers, 2016 to 2020). "The results imply that the cohort of low NKILA expression level was susceptible to a heightened risk of lymph node metastasis in comparison with that of high NKILA expression level." (PMID 32851072, 2020). "Univariate analysis showed that TNM stage, NKILA expression, and lymph node metastasis caused more obvious differences in overall survival time; multivariate analysis showed that low NKILA expression was of high risk (HR = 0.389, 95% CI = 0.152–0.993)." (PMID 29573243, 2018). "In TSCC the low expression level of NKILA was associated with tumor size, advanced clinical staging, lymph node metastasis and poor survival, indicating that the low NKILA expression may promote an aggressive phenotype of TSCC and serve as a prognostic marker." (PMID 27613832, 2016). "A collection of three studies presented findings on the relationship between NKILA expression and lymph node metastasis." (PMID 32851072, 2020). "The expression of NKILA is negatively correlated with NSCLC lymph node metastasis suggest NKILA could be an effective marker and target for antimetastasis therapies." (PMID 28412955, 2017). "Decreased NKILA expression level in TSCC was significantly correlated with tumor size (P=0.001), advanced clinical staging (P=0.001) and lymph node metastasis (P=0.001)." (PMID 27613832, 2016). "NKILA expression was also lower in tumor tissues with lymph node metastasis than in tumor tissues without lymph node metastasis, but the difference between the two groups was not significant (p = 0.076), perhaps because the sizes of the samples were small." (PMID 29379981, 2018). "The expression of NKILA was down-regulated in NSCLC cancer tissues compared with matched adjacent noncancerous tissues, and lower NKILA expression in tumor tissues were significantly correlated with lymph node metastasis and advanced TNM stage." (PMID 28412955, 2017).
melanoma (5 papers, 2022 to 2024). A malignant, usually aggressive tumor composed of atypical, neoplastic melanocytes. "Further, NKILA significantly induced apoptosis and inhibited invasion in melanoma cell lines through regulation of the nuclear factor kappa B (NF‐ĸB) signalling pathway." (PMID 38193829, 2024). "Many studies have demonstrated over- or under-expression of particular types of lncRNAs, such as HOXA6, FDG5-AS1, PVT1, and NKILA in patients with melanoma as a result of developments in sequencing methods." (PMID 39777348, 2024). "In melanomas, NKILA inhibits invasion and metastasis dissemination through the inhibition of NFκB signaling." (PMID 35159386, 2022). "Moreover, NKILA effectively reduced invasion and triggered apoptosis in melanoma cell lines by controlling the nuclear factor kappa B (NF-θB) signaling trail." (PMID 39777348, 2024). "With the advancements in sequencing technologies, many studies have shown over‐ or under‐expression of specific types of lncRNAs, such as NKILA, PVT1, FDG5‐AS1 and HOXA6, in patients with melanoma." (PMID 38193829, 2024).
non-small cell lung carcinoma (5 papers, 2017 to 2022). A group of at least three distinct histological types of lung cancer, including non-small cell squamous cell carcinoma, adenocarcinoma, and large cell carcinoma. "A recent study showed that NKILA was downregulated in non-small cell lung cancer and suppressed EMT through interfering NF-κB/Snail signal pathway." (PMID 29348395, 2018). "Therefore, NKILA acts as a tumor suppressor against breast cancer progression and metastasis, tongue squamous cell carcinoma cells and in non-small cell lung cancer (NSCLC)." (PMID 30018188, 2018). "However the clinical significance and biological role of NKILA in non-small cell lung cancer (NSCLC) remains unknown." (PMID 28412955, 2017). "NKILA is a potent predictor for overall survival and a vital determinant of EMT in tongue squamous cell carcinoma, melanoma and non-small cell lung cancer." (PMID 29348395, 2018). "Although downstream effectors were tumor specific, NKILA mediated NF-κB abrogation in suppression of EMT was consistent in tongue squamous cell carcinoma, non-small cell lung cancer and ESCC." (PMID 29348395, 2018). "Moreover, NKILA-mediated NF-κB activation can be regarded as a therapeutic molecule since it inhibits EMT and suppresses the advancement of cancer; this is evident in breast cancer, hepatocellular carcinoma, osteosarcoma, and non-small-cell lung cancer." (PMID 32851072, 2020).
Sepsis (5 papers, 2021 to 2024). Sepsis is defined as life-threatening organ dysfunction caused by a dysregulated host response to infection. "In another study, NKILA knockdown increased cell viability and suppressed autophagy, cell apoptosis, and inflammation in a lipopolysaccharide-induced sepsis model." (PMID 39184397, 2024). "LncRNA NKILA silencing protected HK-2 cells from sepsis-mediated AKI by decreasing CLDN2 through sponging miR-140-5p." (PMID 37215112, 2023). "In sepsis rats, lncRNA NKILA and the expression of autophagy-related proteins were significantly increased in kidney tissues, and lncRNA NKILA regulated the autophagy via PI3K/Akt pathway." (PMID 35464083, 2022). "Downregulation of NKILA restrained apoptosis, autophagy and inflammation and promoted viability in sepsis-induced AKI." (PMID 34956235, 2021).
esophageal squamous cell carcinoma (4 papers, 2018 to 2024). Esophageal squamous cell carcinoma (ESCC) is a type of esophageal carcinoma (EC) that can affect any part of the esophagus, but is usually located in the upper or middle third. "It has been reported that NKILA was poorly expressed in esophageal squamous cell carcinoma tissues and cells, which is consistent with our results." (PMID 33686956, 2021). "However, the clinical significance and biological roles of NKILA in esophageal squamous cell carcinoma (ESCC) remain unknown." (PMID 29348395, 2018).
nasopharyngeal carcinoma (4 papers, 2019 to 2022). A carcinoma arising from the nasopharyngeal epithelium. "NKILA was also found to suppress nasopharyngeal carcinoma carcinogenesis and metastasis via NF-kappaB pathway inhibition." (PMID 34391383, 2021). "In our study, we first discovered that a long non-coding RNA named NKILA which was down-regulated in nasopharyngeal carcinoma, and we have demonstrated that overexpression of NKILA repressed the motile behavior and metastatic capacity of NPC cells." (PMID 31430288, 2019). "But the role of NKILA in nasopharyngeal carcinoma remains unknown." (PMID 31430288, 2019). "NKILA might be a vital gene for repressing the role of EBV and become one of the most important therapeutic targets for patients with nasopharyngeal carcinoma." (PMID 31430288, 2019).
tongue squamous cell carcinoma (4 papers, 2018 to 2022). A squamous cell carcinoma that arises from the tongue. "Low NKILA expression has been implicated in tongue squamous cell carcinoma invasion and metastasis." (PMID 32334623, 2020).
brain injuries (2 papers, 2021 to 2022). "In traumatic brain injury, astrocytes show increased expression and secretion of the lncRNA NKILA, which exerts neuroprotective properties by depleting miR-195, an miRNA associated with apoptosis." (PMID 36567359, 2022). "For instance, the lncRNA NKILA is differentially expressed in ICH and protects against brain injuries." (PMID 34288826, 2021).
colorectal cancer (2 papers, 2021 to 2022). A primary or metastatic malignant neoplasm that affects the colon or rectum. "lncRNA NKILA plays a crucial role in constraining tumor progression in a variety of cancer types, including colorectal cancer." (PMID 35300596, 2022). "Moreover, we verified the relationship among LINC00174, NKILA, and autophagy in colorectal cancer cells." (PMID 34692467, 2021). "LINC00174 and NKILA were expressed in the nucleus and cytoplasm of normal colonic epithelial cell line NCM460 and colorectal cancer cell lines HT29." (PMID 34692467, 2021). "As shown in results, NKILA and LINC00174 were all higher expressed in colorectal cancer cell line HT29 compared to normal colonic epithelial cell line NCM460." (PMID 34692467, 2021). "In our research, we found that NKILA and LINC00174 were related to autophagy in colorectal cancer." (PMID 34692467, 2021). "However, at present, no study has found whether LINC00174 and NKILA can affect the occurrence and development of colorectal cancer through autophagy, which will also be the focus of our follow-up research." (PMID 34692467, 2021).
diffuse large B-cell lymphoma (2 papers, 2022 to 2023). "For example, in diffuse large B-cell lymphoma (DLBCL), the lncRNA NKILA is often silenced through hypermethylation of its promoter region, which leads to increased cellular proliferation and decreased cell death." (PMID 37345170, 2023). "In 102 NHL primary samples, NKILA was methylated in 29 (51.79%) diffuse large B-cell lymphoma (DLBCL) and 4 (20%) peripheral T-cell lymphoma cases, but unmethylated in all 26 mantle cell lymphoma cases." (PMID 35052468, 2022).
retinoblastoma (2 papers, 2020 to 2021). A malignant tumor that originates in the nuclear layer of the retina. "Compared to healthy controls, lncRNA Xist was significantly upregulated in plasma of retinoblastoma patients which was inversely associated with lncRNA NKILA." (PMID 34178980, 2021). "In many types of malignant tumors, such as breast cancer, rectal cancer, tongue squamous cell carcinoma, retinoblastoma, laryngeal cancer, malignant melanoma, and non-small cell lung cancer, NKILA suppresses NF-kappa B-mediated cancer metastasis." (PMID 32382013, 2020). "LncRNA Xist overexpression promotes retinoblastoma cells proliferation, migration, and invasion rates via negatively regulating lncRNA NKILA, but the causality has not been fully validated." (PMID 34178980, 2021).
acute kidney injury (1 paper, 2021). Sudden and sustained deterioration of the kidney function characterized by decreased glomerular filtration rate, increased serum creatinine or oliguria. "In addition, NKILA can enhance autophagy of HK2 cells through Mir-140-5p/CLDN2/LPS pathway to induce acute kidney injury." (PMID 34692467, 2021).
asthma (1 paper, 2022). "In asthma, NKILA could limit airway inflammation by promoting M2 macrophage polarization and inhibiting the NF-κB pathway." (PMID 35335994, 2022). "NKILA was reported to have inhibitory roles on NF-κB in HIV and asthma." (PMID 35335994, 2022).
atherosclerosis (1 paper, 2024). A disease characterized by the build-up of fatty material and calcium deposition in the arterial wall resulting in partial or complete occlusion of the arterial lumen. "Expression research has confirmed the downregulation of the NKILA in patients with atherosclerosis compared to the patients in the control group." (PMID 39184397, 2024). "In this study, the hypothesis is that NKILA may regulate endothelial cell (EC) apoptosis and, therefore, play a role in the pathogenesis of atherosclerosis." (PMID 39184397, 2024). "The expression detection of all these genes, resulting from NKILA gene silencing, may provide guidance for epigenetic studies on EC apoptosis in atherosclerosis." (PMID 39184397, 2024). "This hypothesis is based on the knowledge that EC apoptosis contributes to atherosclerosis development and that NKILA has become a prominent lncRNA in CVDs." (PMID 39184397, 2024). "The novelty of the study is that lncRNA NKILA may play a role in regulating EC apoptosis, which is induced by ox-LDL during the initial stage of atherosclerosis." (PMID 39184397, 2024).
bladder cancer (1 paper, 2020). "Moreover, Kaplan-Meier analysis indicated that among patients with bladder cancer treated with immunotherapy, low NKILA expression resulted in longer OS compared with high NKILA expression (HR, 0.64; 95% CI, 0.49-0.83; P < .001)." (PMID 32259264, 2020).
cerebral infarction (1 paper, 2023). An ischemic condition of the brain, producing a persistent focal neurological deficit in the area of distribution of the cerebral arteries. "For example, one study found that lncRNA NKILA significantly alleviated the extent of cerebral infarction, brain edema, and neurological damage." (PMID 37480035, 2023).
cervical squamous cell carcinoma (1 paper, 2024). A squamous cell carcinoma arising from the cervical epithelium. "Overexpression of the NKILA was reported to suppress proliferation and induce apoptosis of cervical squamous cell carcinoma cells (Wang, Zhu & Qiu, 2020)." (PMID 39184397, 2024).
colon cancer (1 paper, 2022). "NKILA and BOLA3-AS1 have been identified as unfavorable factors for colon cancer, which is consistent with the findings of this study." (PMID 35912098, 2022).
diabetes (1 paper, 2022). "NKILA plasma levels six months before diagnosis were sufficient to distinguish DCM patients from other diabetes patients." (PMID 36552599, 2022). "However, plasma NKILA levels were not significantly altered in patients with diabetes and other complications, further implicating the specific involvement of lncRNA NKILA in DCM." (PMID 36552599, 2022).
diabetic cardiomyopathy (1 paper, 2024). Diabetic cardiomyopathy is a disorder of the heart muscle in people with diabetes. "In another study on diabetic cardiomyopathy, it was reported that NKILA was highly expressed in high sugar-induced AC16 cells, and apoptosis protein markers such as BAX, CASP3, and CASP9 were increased, while anti-apoptosis protein BCL-2 was inhibited." (PMID 39184397, 2024). "In diabetic cardiomyopathy patients, ectopic lncRNA NKILA expression enhances cardiomyocyte apoptosis, whereas NKILA knockdown inhibits cardiomyocyte apoptosis (Li, Li & Su, 2019)." (PMID 39184397, 2024).
Hodgkins lymphoma (1 paper, 2022). A heterogeneous group of malignant lymphoid neoplasms of B-cell origin characterized histologically by the presence of Hodgkin and Reed-Sternberg (HRS) cells in the vast majority of cases. "As the constitutive activation of the NF-κB signaling pathway is the hallmark of many lymphoid malignancies, including Hodgkin’s lymphoma and DLBCL, and hence implicated in lymphomagenesis, it is essential to comprehend the precise function of NKILA and its interaction with NF-κB in lymphomas." (PMID 35052468, 2022).
lymphoma (1 paper, 2022). A malignant (clonal) proliferation of B- lymphocytes or T- lymphocytes which involves the lymph nodes, bone marrow and/or extranodal sites. "As NKILA was a negative regulator in NF-κB signaling pathways, its tumor suppressor function in lymphoma was further explored by examining cell proliferation and cell death in SU-DHL-1 cells that were completely unmethylated for NKILA." (PMID 35052468, 2022). "We observed that the knockdown of NKILA led to the upregulation of NF-κB signaling pathways by promoting IκBα phosphorylation, and the consequent nuclear translocation of total p65 and phosphorylated p65 in lymphoma cells." (PMID 35052468, 2022).
major depressive disorder (1 paper, 2022). An episode of depression lasting two or more weeks without an intervening episode of mania. "NEAT1, PCAT1, RMRP, and NKILA are lncRNAs associated with neuropsychiatric phenotypes such as major depressive disorder (MDD), addictive behavior, and substance abuse." (PMID 36005827, 2022).
non-Hodgkin lymphoma (1 paper, 2022). Distinct from Hodgkin lymphoma both morphologically and biologically, non-Hodgkin lymphoma (NHL) is characterized by the absence of Reed-Sternberg cells, can occur at any age, and usually presents as a localized or generalized lymphadenopathy associated with fever and weight loss. "As a CpG island is embedded in the promoter region of NKILA, it is hypothesized as a tumor suppressor lncRNA silenced by promoter DNA methylation in non-Hodgkin’s lymphoma (NHL)." (PMID 35052468, 2022).
ovarian carcinoma (1 paper, 2024). A malignant neoplasm originating from the surface ovarian epithelium. "Having observed a possible role of NKILA in c-Myb signaling and cisplatin resistance of ovarian cancer cells, we next evaluated if NKILA could play a role in different characteristics associated with cancer cells." (PMID 38745302, 2024). "The further observation of an increased NF-κB signaling in cells with downregulated NKILA confirms the NF-κB-targeting activity of lncRNA NKILA as well as its role in cisplatin resistance of ovarian cancer cells." (PMID 38745302, 2024). "We provide first evidence for the role of lncRNA NKILA in cisplatin resistance of ovarian cancer." (PMID 38745302, 2024). "In conclusion, in this study we provide a mechanism for C-Myb-mediated cisplatin resistance of ovarian cancer cells that involves downregulated lncRNA NKILA, activated NF-κB signaling, increased stemness marked by LIN28A and the resulting downregulated let-7 family of miRNAs." (PMID 38745302, 2024). "Combined, the results showed that whereas NKILA affects invasion and colony forming ability of ovarian cancer cells, it does not seem to have any effect on cell proliferation or cell cycle progression." (PMID 38745302, 2024).
tongue cancer (1 paper, 2018). A malignant neoplasm affecting the tongue. "Because over-activated NF-κB signaling have been associated with malignant transformation of several human cancers including ESCC and NKILA was reported to suppress activation of NF-κB in breast and tongue cancer, we asked whether NKILA could inhibit NF-κB in ESCC." (PMID 29348395, 2018).